PKD1 (polycystin 1, transient receptor potential channel interacting)
Diseases named in the same sentence as PKD1 in open-access papers (continued):
Sharing a sentence is not in itself a finding about the gene and the disease.
tumor (62 papers, 2009 to 2026). "Based on this work, we define Pkd1 loss as tumor suppressive for CRC, based on cell-intrinsic activity in the colon epithelium." (PMID 37542051, 2023). "These mice were crossed to mice with a floxed Pkd1 allele, to compare tumor formation in Apc−/−, Apc−/−;Pkd1-/+, and Apc−/−;Pkd1−/− mice." (PMID 37542051, 2023). "To gain insight into the mechanism by which Pkd1 loss reduced tumor growth, we considered that in ADPKD, Pkd1 loss activates the cystic fibrosis transmembrane receptor (CFTR), contributing to polarized ion secretion." (PMID 37542051, 2023). "Tumor associated endothelial cells (TAECs) exposed to LPA demonstrated sustained nuclear PKD-1 phosphorylation, and elevated mRNA levels of ephrin B2, and reduced mRNA expression of CD36." (PMID 28186980, 2017). "In tamoxifen-treated patients, tumours with high PKD1 mRNA levels (n = 77, 50.66%) were significantly associated with less metastasis-free survival than tumours with low PKD1 mRNA expression (n = 75, 49.34%; P = 0.031)." (PMID 25287328, 2014). "Due to these molecular alterations, PKD1 overexpression causes conspicuous change in tumor morphology, structure and histo-architecture." (PMID 25149539, 2014). "In particular, PKD1 has been implicated in many aspects of tumor development, such as tumor growth, metastasis, and angiogenesis." (PMID 24086585, 2013). "PKD1 has previously been implicated in the control of actin reorganisation and tumor cell migration." (PMID 23717204, 2013). "One explanation might be the fact that while loss of Pkd1 is growth-inhibitory in a cell-autonomous manner in vitro, factors in the nascent tumor microenvironment—perhaps mediated by immune system components—ameliorate this effect in vivo." (PMID 37542051, 2023). "Although these signaling pathways have been reported to be distinctly linked to various diseases, the exact role of PKD1 remains unclear, particularly in neoplasia." (PMID 34858418, 2021). "Finally, earlier studies have connected PKD1 mutations and CRC risk, and also suggested that elevated levels of PKD1 in late-stage tumors and tumor-derived cell lines are associated with more invasive phenotypes due to increased EMT and migration, and worse survival." (PMID 37542051, 2023). "The reduced incidence of Pkd1-deficient tumors might solely reflect cell intrinsic consequences of Pkd1 loss in colon epithelial cells or might instead reflect the altered interaction of PKD1-deficient epithelial cells with the nascent tumor microenvironment." (PMID 37542051, 2023). "Thus, the upregulation of PKD1 as a result of inhibition or loss of AR may promote tumor cell survival and contribute to therapeutic resistance to AR-targeted agents." (PMID 28077787, 2017). "Interestingly, PKD-1 signaling appears to regulate tumor angiogenesis and is implicated in tumor arteriogenesis as it may regulate CD36 expression and vascular remodeling in the tumor microenvionment." (PMID 27200349, 2016). "The primary tumor showed few genomic alterations with a deletion of the PKD1 and TSC2 region on chromosome 16, a LOH of the 17p region, a deletion of chromosome 18, and a partial deletion of chromosome 19." (PMID 41416936, 2026). "The mechanisms are unresolved, but the human PKD1 tumor suppressor is a good experimental model for identifying the molecular determinants." (PMID 39747084, 2025). "Restoring the normal methylation pattern of this gene with decitabine affected tumor aggressiveness and inhibited tumor spread in a PKD1-dependent manner." (PMID 37108398, 2023). "Quantification of tumor size indicated that tumors emerging in Apc−/−;Pkd1-/+, and Apc−/−;Pkd1−/− mice were significantly smaller than tumors in Apc−/− mice." (PMID 37542051, 2023). "To determine if the PKD1 pathway was associated with CSCs in pNETs, we further observed the expression of PKD1 and CD44 in tumor tissues from human pNET patients." (PMID 36497140, 2022).
tumor (continued). "Several investigations have shown that PKD1 plays a role in the regulation of various tumor-related pathways." (PMID 35707371, 2022). "Concomitantly, tumorsphere formation capacity was impaired in these tumor cells with PKD1 knockdown." (PMID 36497140, 2022). "Lysophosphatidic acid (LPA), a lipid signaling mediator, activates PKD1 and promotes tumor initiation, the development of CSC-like features and metastasis." (PMID 36497140, 2022). "In cancer, PKD1 plays different roles depending on tumor type, both pro-tumorigenesis and anti-tumor." (PMID 34249722, 2021). "Several genetically modified mouse models were developed to study PKD1 involvement in tumor initiation and progression in vivo." (PMID 33807058, 2021). "A subpopulation of BC cells showed high levels of PKD-1 expression, particularly in the tumor nests, whereas singular BC cells had a moderate expression of PKD-1." (PMID 34168243, 2021). "To validate the role of LPA/PKD-1 signaling in supporting BCSC stemness, we evaluated the impact of PKD-1 depletion on BCSC tumor-initiating potential in well-established in vitro limiting dilution tumor assays." (PMID 34168243, 2021). "BCSCs with high CD36 and moderate PKD-1 expression were localized outside of the tumor nest and had invaded into the surrounding tissue, whereas the BCSCs with low CD36 and moderate PKD-1 expression appeared to form a vessel-like structure or capillary." (PMID 34168243, 2021). "Overall, these results show that BPA promoted tumor growth in vivo and that PKD1 expression levels modulated the cellular response to this endocrine disruptor." (PMID 32082170, 2019). "We previously demonstrated that PKD1 overexpression potentiates in vivo tumor growth of the MCF-7 adenocarcinoma-derived cell line, and regulates cell growth." (PMID 32082170, 2019). "We utilized these available tumor samples to determine if PKD1 regulates phosphorylation of PIP5K1C in vivo." (PMID 30555634, 2018). "In normal squamous mucosa, strong membranous pattern of PKD1 staining as well as diffused or granular cytoplasmic staining of PKD1 were observed, which is in contrast to the weak and diffused cytoplasmic staining of PKD1 in tumor tissues." (PMID 30419840, 2018). "The pattern of PKD1 expression was further confirmed in a small cohort of patient-paired head and neck normal and tumor tissue samples." (PMID 30419840, 2018). "The current study was undertaken to evaluate the expression of PKD1 in HNSCC tumor specimens and cell lines to gain insights into its clinical significance." (PMID 30419840, 2018). "PKD1 expressed abundantly in the normal squamous mucosa (enlarged image, left), but little was detected in the adjacent tumor tissues (enlarge image, right)." (PMID 30419840, 2018). "PKD1 protein expression was further assessed by IHC in a set of 6 patient-paired head and neck normal and tumor tissue samples." (PMID 30419840, 2018). "Among the tumor specimens, six (5%) showed strong PKD1 expression, ten (8%) moderate, 49 (40%) weak, and 58 (47%) were negative." (PMID 30419840, 2018). "In human HNSCC tissues, PKD1 was significantly down-regulated in localized tumors and metastases, and in patient-paired tumor tissues as compared to their normal counterparts, which was in part due to epigenetic modification of the PRKD1 gene." (PMID 30419840, 2018). "Accordingly, IHC staining showed increased cell proliferation (Ki67) in tumor explants of the Dox-treated PKD1-c1 group as compared with the controls." (PMID 30419840, 2018). "Tumor tissues were subsequently analyzed by Western blotting for PKD1 expression and downstream signaling activity." (PMID 30419840, 2018). "PKD1 has been shown to regulate tumor cell proliferation, survival, migration, and invasion in multiple cancers." (PMID 30419840, 2018). "KRas/mROS/PKD1/NF-κB signaling contributes to tumor initiation by upregulating expression of EGFR and its ligands TGFα and EGF." (PMID 28361035, 2017).
tumor (continued). "Since oxidative stress activates protein kinase D1 (PKD1) in tumor cells, we investigated the effect of excitotoxicity on neuronal PKD1 activity." (PMID 29273751, 2017). "This mini-review focuses on a ROS-sensing signaling pathway that controls tumor cell detoxification, proliferation, and survival through activation of protein kinase D1 (PKD1)." (PMID 28361035, 2017). "PKD-1 is also a key regulator of gene expression and angiogenesis that is essential for cardiovascular development and tumor progression." (PMID 27200349, 2016). "In tumor angiogenesis, endothelial PKD1 has a positive regulatory function as the part of the VEGFR2 signaling pathway." (PMID 25874616, 2015). "Analysis of the time taken for visible tumor formation (volume of 50mm3 or more) in each animal clearly showed a delay in tumor appearance in the PKD1 overexpressing cells compared to control group." (PMID 25149539, 2014). "Studies in a xenograft mouse model indicate that PKD1 overexpression delayed tumor appearance, enhanced necrosis and lowered tumor hypoxia." (PMID 25149539, 2014). "Together, these results suggest that the overexpression or activation of PKD1 in tumors enhanced tumor cell death and lowered hypoxia within the tumors." (PMID 25149539, 2014). "Overall, our results demonstrate a putative tumor-suppressor function of PKD1 in colon tumorigenesis via modulation of β-catenin functions in cells." (PMID 25149539, 2014). "Among others, PKD1 overexpressing cells acquire the ability to grow independently of anchorage and to form tumours in nude mice." (PMID 25287328, 2014). "To investigate the tumor suppressor potential of PKD1 in colon carcinogenesis in-vivo, we examined the tumor growth pattern of PKD1 overexpressing cells in a xenograft mouse model." (PMID 25149539, 2014). "The in-vivo investigation using a xenograft mouse model revealed that PKD1 overexpression delayed the time of tumor appearance and tumor development compared to control GFP overexpressing cells." (PMID 25149539, 2014). "Equal number of SW480 cells overexpressing PKD1 or control vector (GFP) were subcutaneously (sc) injected into the hind flank of nude mice for tumor formation (n=8 per group)." (PMID 25149539, 2014). "Further analysis of patient sample and PKD1 activators in animal mouse models will yield important information on the role of PKD1 in tumor metastasis and the development of effective treatment strategies." (PMID 25149539, 2014). "Our data show that PKD1 is widely expressed in zebrafish and contributes to physiological angiogenesis but is crucial only for tumor angiogenesis in the zebrafish/tumor xenograft angiogenesis assay." (PMID 23874489, 2013). "Of note, some heterogeneity in the intensity of PKD1 expression in different areas of each tumor sample was detected, probably due to decitabine delivery to the tumor (not shown)." (PMID 23971832, 2013). "In a conclusion, PKD1 contributes to physiological angiogenesis and lymphangiogenesis in vivo and is critically required for tumor angiogenesis in the zebrafish model." (PMID 23874489, 2013). "Co-Mo or PKD1 SB-Mo I5 were injected in the 1-cell or 2-cell stage of tg(fli1:EGFP) zebrafish embryos followed by injection of a HCT116 tumor cell-matrigel solution in the perivitelline space at 48 hpf." (PMID 23874489, 2013). "Overexpression of PKD1 or PKD3 almost completely reversed the growth arrest and the inhibition of tumor cell invasion caused by 1-NA-PP1, indicating that its anti-proliferative and anti-invasive activities were mediated through the inhibition of PKD." (PMID 24086585, 2013). "The aim of our study was to define the contribution of PKD1 to physiological and tumor angiogenesis in an established model system in vivo." (PMID 23874489, 2013).
tumor (continued). "Using an animal model, we show that reversion of PRKD1 promoter methylation with the DNA methyltransferase inhibitor decitabine restores PKD1 expression and blocks tumor spread and metastasis to the lung in a PKD1-dependent fashion." (PMID 23971832, 2013). "To analyze the function of PKD1 in tumor angiogenesis in zebrafish we used the zebrafish/tumor xenograft angiogenesis assay." (PMID 23874489, 2013). "Here we aimed at dissecting the contribution of PKD1 to physiological angiogenesis and tumor angiogenesis in vivo in zebrafish." (PMID 23874489, 2013). "This suggested that observed inhibitory effects of decitabine treatment on local tumor cell invasion and primary tumor expansion are dependent on upregulation of PKD1 expression." (PMID 23971832, 2013). "Our data show that silencing of PKD1 almost completely prevented tumor angiogenesis induced by HCT116 cells as determined by ectopic sprouting of the subintestinal venous plexus." (PMID 23874489, 2013). "In conclusion, our data show that PKD1 is sufficient and also required for tumor angiogenesis of HCT116 in the zebrafish model demonstrating a major role of host-PKD1 in the regulation of tumor angiogenesis." (PMID 23874489, 2013). "Our data in zebrafish demonstrate that PKD1 contributes to the regulation of physiological angiogenesis and lymphangiogenesis during zebrafish development and is essential for tumor angiogenesis." (PMID 23874489, 2013). "Overexpression of PKD1 in C4-2 induces expression of E-cadherin and lowers tumor incidence in mice xenograft models." (PMID 22511927, 2012). "Little is known about the role of PKD1 in regulating tumour cell migration and invasion, important processes that regulate both tumour expansion and metastasis." (PMID 19243594, 2009). "This comprehensive genomic characterization of metastases enhances our understanding of tumor evolution, identifies PKD1 as a previously uncharacterized regulator of immune evasion to our knowledge, and suggests a potential therapeutic strategy to overcome immunotherapy resistance." (PMID 41766665, 2026). "Multi-omics analyses, combined with functional in vitro and in vivo mechanistic studies, revealed that PKD1 modulated the "desert" tumor immune microenvironment via C-C motif chemokine ligand 2 (CCL2), and targeting CCL2 could reverse immunotherapy resistance." (PMID 41766665, 2026). "It is unknown why many tumor suppressors follow this pathway, or why orthologous genes in animal models are often genetically stable, but the human PKD1 (hPKD1) gene presents a unique experimental opportunity to uncover a mechanism." (PMID 39747084, 2025). "Furthermore, pharmacologic reversion of PRKD1 methylation with the DNA methyltransferase inhibitor decitabine restored PKD1 expression and reduced tumor invasion and metastasis to lungs in an animal model." (PMID 37293129, 2023). "Notably, Pkd1 loss caused greater sensitivity to activation of CFTR, a tumor suppressor in CRC, paralleling signaling relations in ADPKD." (PMID 37542051, 2023). "On the other hand, re-expression of PKD1 to rescue its tumor suppressive functions in terms of invasiveness and metastasis by general suppression of methylation using the epi-drug decitabine has shown promising results in in vivo models, but the compound is not specific to PKD1." (PMID 37293129, 2023). "LPA as a PKD1 activator regulates an EMT program in tumor progression." (PMID 36497140, 2022). "Among many biological outcomes of PKD1 signaling are increased angiogenesis and tumor progression." (PMID 36497140, 2022). "In vitro experiments have shown that the PKD1 gene promotes cell adhesion and attenuates metastasis and the invasion of tumor cells, suggesting that it may have been involved in tumor suppression." (PMID 36540879, 2022). "Targeting the LPA/PKD-1 -CD36 signaling pathway may have therapeutic potential to curb tumor progression by disrupting the arteriolar niche and effectively eliminating CSCs." (PMID 34168243, 2021).
tumor (continued). "Thus, PKD1–3 have all been reported to promote tumor cell growth and proliferation through both shared and distinctive signaling pathways." (PMID 33807058, 2021). "Compared to PKD1, PKD2 and PKD3 are often associated with tumor progression." (PMID 34249722, 2021). "Interestingly, lung NET patients have demonstrated comparable levels of PKD1 mRNA in blood and tumor tissues." (PMID 33138224, 2020). "However, PKD1 over- and underexpression has been observed in several cancer types, with the expression profile being specific to tumor tissue." (PMID 33138224, 2020). "PKD1 inhibition also reduced tumor growth in vivo in a TNBC PDX model." (PMID 29796183, 2018). "Thus, the functional relevance of PKD1 to tumor initiation and progression remains to be determined." (PMID 30419840, 2018). "To examine whether pharmacological inhibition of PKD1 could inhibit tumor growth in vivo, we decided to evaluate the antitumor activity of the AB9275 molecule in a TNBC patient-derived xenograft (PDX) model." (PMID 29796183, 2018). "However, the median growth rate of the subcutaneous HNSCC tumor xenografts over time was elevated with PKD1 induction, and the final tumor weight was significantly increased in Dox-induced vs. the non-induced tumors." (PMID 30419840, 2018). "Additionally, we observed that LPA/PKD-1 signaling is activated in the tumor endothelium possibly via the G-protein coupled receptor LPA receptor 1 (LPA1)." (PMID 28186980, 2017). "Indeed, the phosphorylation levels of PKD-1 were increased in the tumor endothelium in chronic DIO mice." (PMID 28186980, 2017). "Since a strong increase in the expression of the Gö6976-target « PKD1 » is observed in M2 metastatic cells in comparison to their corresponding primary tumor cells (I5), overexpression of this serine/threonine kinase could be one of these events." (PMID 28056869, 2017). "However, the comparison between the two groups of tumors only showed a limited 3-fold over-expression in CA9 and a 2-fold over-expression in PKD1, in the 21% O2 tumor group as compared to the 3% O2." (PMID 27788227, 2016). "Furthermore, PKD-1 signaling is essential for VEGF signaling-mediated angiogenic functions and is implicated in tumor arteriogenesis." (PMID 27200349, 2016). "Furthermore, restoration of PKD1 expression showed a significant decrease in the quantity of tumor cells expressing MMP-9 as compared to mice implanted with MDA-MB-231 cells expressing PKD1-shRNA (block of decitabine-mediated restoration of PKD1 expression)." (PMID 26848698, 2016). "Importantly, kinome analysis revealed that weight loss reversed HFD-upregulated activity of PKC-α, PKD1, PKA, and MEK3 and increased AMPKα activity in unaffected mammary glands isolated prior to tumor latency." (PMID 27042159, 2016). "However, PKD1 overexpression in SW480 cells delayed the tumor appearance in nude mice compared to control SW480 cells overexpressing empty vector." (PMID 25149539, 2014). "Indeed, tumor tissues formed by PKD1 overexpressing cells showed much lower expression of Glut1 compared to control tumors." (PMID 25149539, 2014). "In-vitro and in-vivo studies using xenograft mouse model revealed that PKD1 overexpression suppresses cell proliferation, clonogenic potential, enhances cell-cell aggregation and alters the tumor histo-architecture via modulation of β-catenin functions in cells." (PMID 25149539, 2014). "Consequently, when compared with tumours expressing low PKD1 mRNA levels ≤0.38 (n = 75, 49.34%), tumours with high PKD1 mRNA expression >0.38 (n = 77, 50.66%) were significantly associated with less MFS (P = 0.031)." (PMID 25287328, 2014). "In addition, PKD1 overexpression also significantly decreased the average tumor size (volume) in nude mice compared to the tumor formed by control GFP overexpressing cells." (PMID 25149539, 2014). "It would be therefore essential to investigate the role of PKD1 in other tumor types." (PMID 23874489, 2013).